ATRIP (ATR interacting protein)
Diseases named in the same sentence as ATRIP in open-access papers:
ATRIP is named in the same sentence as 19 diseases in open-access papers, as found by Europe PMC text mining. Sharing a sentence is not in itself a finding about the gene and the disease. The quoted sentences say what the papers report.
Seckel syndrome (11 papers, 2012 to 2025). A rare autosomal recessive inherited syndrome caused by mutations in the ATR gene, RBBP8 gene, CENPJ gene, CEP152 gene, CEP63 gene, NIN gene, DNA2 gene, or TRAIP gene. "Mutations in key mediators of the replication stress response, the mutually dependent partners ATR and ATRIP, are among the known causes of Seckel syndrome." (PMID 32994318, 2020). "Mutations in ATR (ATM and rad3-related) and in ATRIP (ATR-interacting protein) are among the causes of Seckel syndrome." (PMID 32630049, 2020). "The identification of an ATRIP–deficient patient provides a novel genetic defect for Seckel Syndrome." (PMID 23144622, 2012). "Similarly, microcephaly also results from mutation in genes associated with S phase progression (ATR, ATRIP, CtIP—Seckel syndrome; DNA ligase IV—lig4 syndrome; XRCC4—microcephalic primordial dwarfism)." (PMID 34035299, 2021). "Seckel syndrome is genetically heterogeneous, and mutations in DDR genes (ATRIP and ATR), DNA repair factors (NSMCE2, DNA2, TRAIP and CtIP) and components of the centrosome (NIN, CEP63, CEP152 and CENPJ) have been reported." (PMID 32994318, 2020). "In particular, our results reveal a causal relationship between a cellular mechanism (progenitor cell death caused by defective RSR) and a CNS dysfunction (loss of vision), elucidating the neurodevelopmental defects in a model of ATRIP-Seckel syndrome." (PMID 32994318, 2020). "Mutations in Ataxia Telangiectasia and Rad3-related (ATR) or in ATR-interacting protein (ATRIP) lead to Seckel syndrome, which is characterized by developmental malformations and short life expectancy." (PMID 33110058, 2020). "In summary, the role of ATRIP during development supports its relationship with Seckel syndrome etiology." (PMID 33110058, 2020). "Seckel syndrome is caused by mutations in DNA damage response signaling and centriole biogenesis factors (ATR, ATRIP, CEP152, CENPJ)." (PMID 28630177, 2017). "This is reflected by patients with the rare genetic disorder Seckel syndrome, to date originating from a small number of families carrying germline mutations in either ATR, or its interacting partner ATRIP, that result in reduced ATR protein levels." (PMID 24416382, 2014). "Here, we provide the first identification of a Seckel Syndrome patient with mutations in ATRIP, the gene encoding ATR–Interacting Protein (ATRIP), the partner protein of ATR required for ATR stability and recruitment to the site of DNA damage." (PMID 23144622, 2012). "Germline pathogenic variants in ATRIP and ATR are known to cause Seckel syndrome, a rare disorder characterized by growth impairment and neurodevelopmental abnormalities, and ATR variants have also been linked to several cancer types, including oropharyngeal, skin, cervical, and breast cancers." (PMID 41440239, 2025). "The ATRIP-ATR signalling complex is a central mediator of the replicative stress response (RSR), and mutations in both genes have been reported in Seckel syndrome." (PMID 32994318, 2020). "The contribution of an ATRIP variant to Seckel syndrome has been reported, but not confirmed." (PMID 26919047, 2016). "ATRIP was the second highest ranking gene in 2009 with no co-occurrence with Seckel syndrome." (PMID 26919047, 2016). "It is unlikely transformed cells can survive without MRE11A, RAD50, ATRIP or PALB2 although significantly reduced levels may be tolerated, as evidenced by the ATR expression in Seckel syndrome and hypomorphic MRE11A and RAD50 mutations in ATLD and NBS-like disorder patients, respectively." (PMID 26438152, 2015).
breast carcinoma (4 papers, 2023 to 2025). "The four ATRIP mutation carriers included the cancer-free proband (II-6), the proband’s unaffected sister (II-7), and the two breast cancer-affected nieces of the proband (III-4 & III-6)." (PMID 41440239, 2025). "At the validation, a rare recurrent mutation in ATRIP, c.1152_1155del, was observed in 42 of 16,085 Polish breast cancer patients and in 11 of 9285 controls (OR = 2.14, 95% CI = 1.13–4.28, p = 0.02)." (PMID 41440239, 2025). "Further studies are needed to provide a clearer understanding of the involvement of ATRIP in breast cancer susceptibility, enhance the evaluation of risk and management of patients, and potentially discover novel targets for personalized treatment strategies." (PMID 41440239, 2025). "As the father of these two affected sisters (II-4) was not an ATRIP mutation carrier, we concluded that their mother (proband’s sister, II-5), who had died of breast cancer before this study, was the obligatory carrier of the ATRIP c.1033delC mutation." (PMID 41440239, 2025). "Further studies are required to confirm the role of ATRIP in breast cancer susceptibility, refine risk assessment, and evaluate potential personalized therapeutic strategies." (PMID 41440239, 2025). "Protein-truncating variants in ATRIP were observed among 13 of 8410 breast cancer cases and 3 of 8238 controls in these two datasets (OR = 3.69, 95% CI = 1.43–9.52, p = 0.007)." (PMID 41440239, 2025). "Future studies should focus on examining tumor phenotypes associated with ATRIP mutations in larger carrier cohorts and characterizing the full range of ATRIP variant types associated with breast cancer risk." (PMID 41440239, 2025). "Using advanced genetic testing, we discovered a harmful ATRIP mutation shared by multiple family members, including two who had breast cancer." (PMID 41440239, 2025). "We also showed that breast cancers in women who carry a germline ATRIP mutation have a loss of heterozygosity at the site of the mutation and a deficiency in DNA repair by homologous recombination." (PMID 37510234, 2023). "By analyzing the sequence data of the UK Biobank, we identified ATRIP loss of function variants in 13 of 15,643 breast cancer patients and 40 of 157,943 female controls (OR = 3.28, 95% CI = 1.76–6.14, p < 0.001)." (PMID 37510234, 2023). "We detected ATRIP c.1152_1155del (p.Gly385Ter) founder mutation in 42 of 16,085 unselected Polish breast cancer patients and in 11 of 9285 cancer-free women (OR = 2.14, 95% CI 1.13–4.28, p = 0.02)." (PMID 37510234, 2023). "Our research team recently identified ATRIP as a novel gene that may increase the risk of developing breast cancer." (PMID 41440239, 2025). "Our team recently identified ATRIP as a novel breast cancer susceptibility gene candidate through whole-exome sequencing (WES) of familial breast cancer patients and healthy controls from the Polish founder population, with subsequent validation in both Polish and British cohorts." (PMID 41440239, 2025). "ATRIP is a newly discovered breast cancer susceptibility gene candidate." (PMID 41440239, 2025). "In this comprehensive analysis, ATRIP reached exome-wide significance for the first time, with protein-truncating variants conferring a statistically significant association with increased breast cancer risk, comparable in magnitude to other moderate-penetrance genes such as BARD1." (PMID 41440239, 2025). "Although ATRIP pathogenic variants are very rare in the general population, our findings add to a growing body of evidence suggesting that deleterious variants in this gene may meaningfully contribute to inherited breast cancer predisposition." (PMID 41440239, 2025). "Interestingly, after publishing our results and introducing ATIRP as a novel breast cancer susceptibility gene candidate, a meta-analysis across two other large WES datasets replicated the positive association of ATRIP deleterious mutations with the risk of developing breast cancer." (PMID 41440239, 2025).
breast carcinoma (continued). "Protein-truncating variants in established susceptibility genes BRCA2, BRCA1, CHEK2, PALB2, ATM and MAP3K1 were associated with a risk of breast cancer, while BARD1 and ATRIP met exome-wide significance for the first time." (PMID 41044259, 2025). "We further validated the association of ATRIP deleterious mutations with an increased risk of breast cancer using WES data of 15,643 Caucasian breast cancer patients and 157,943 ethnically matched cancer-free individuals from the UK Biobank (UKB) cohort study." (PMID 41440239, 2025). "In this case report, we describe, for the first time in an Iranian family, a truncating ATRIP variant detected in multiple members with strong clustering of breast cancer and no pathogenic variants in established hereditary breast cancer susceptibility genes." (PMID 41440239, 2025). "In the present study, we report for the first time the detection of a novel deleterious mutation in ATRIP among several members of an Iranian family with clustering of breast cancer who were negative for mutations in the already known breast cancer risk genes." (PMID 41440239, 2025). "Considering the very low mutation frequency of ATRIP, our newly discovered breast cancer susceptibility gene candidate, we did not expect to find an ATRIP mutation in this family and performed WES in search of other new candidate genes." (PMID 41440239, 2025). "Unfortunately, tumor samples of the proband’s two breast cancer-affected nieces that harbored the ATRIP c.1033delC mutation were not available to perform additional studies, including loss of heterozygosity (LOH) analysis." (PMID 41440239, 2025). "Importantly, all exome-sequenced family members were negative for pathogenic variants in the already known breast cancer risk genes, underscoring the potential contribution of ATRIP’s mutation to the familial clustering of the disease in this family." (PMID 41440239, 2025).
Fanconi anemia (4 papers, 2017 to 2025). Fanconi anemia (FA) is a hereditary DNA repair disorder characterized by progressive pancytopenia with bone marrow failure, variable congenital malformations and predisposition to develop hematological or solid tumors. "These include the two HR factors CtIP and RAD51, the early transductors of RS signaling ATR (ataxia telangiectasia and Rad3-related) and ATRIP (ATR interacting protein), and the Fanconi anemia (FA) protein FANCD2 (Fanconi anemia group D2 protein)." (PMID 29206178, 2017). "Although breast tumor tissue from the affected carriers was not available for LOH or HRD assessment, prior studies suggest that impaired ATRIP function may disrupt ATR-mediated checkpoint and the Fanconi anemia repair pathway, both of which are closely linked to HRR." (PMID 41440239, 2025).
microcephaly (4 papers, 2012 to 2025). A congenital or acquired developmental disorder in which the circumference of the head is smaller than normal for the person's age and sex. "All four ATR/ATRIP patients displayed severe microcephaly and growth delay." (PMID 23144622, 2012).
microphthalmia (3 papers, 2020 to 2025). Congenital or developmental anomaly in which the eyeballs are abnormally small. "Nestin-Cre-mediated inactivation of ATRIP in the developing central nervous system and in the eye leads to tissue growth defects (microphthalmia and microcephaly) that mirror the ones observed upon Atr inactivation." (PMID 34805142, 2021).
aphakia (1 paper, 2020). "ATRIP loss in the surface ectoderm (E9) led to aphakia (absence of lens) and eye growth defects (~80% reduction in eye volume at P21)." (PMID 33110058, 2020).
HCMV infection (1 paper, 2014).
Hereditary breast cancer (1 paper, 2025). "Incorporation of ATRIP into such testing pipelines, particularly with the emergence of additional supportive evidence, may improve diagnostic yield for patients with hereditary breast cancer." (PMID 41440239, 2025). "Disruption of this pathway may contribute to tumorigenesis, yet the extent to which ATRIP LoF variants contribute to hereditary breast cancer is still being elucidated." (PMID 41440239, 2025).
lung squamous cell carcinomas (1 paper, 2015). "ATR, ATRIP and TOPBP1 are altered in 45/212 lung squamous cell carcinomas (21 %) in the TCGA database." (PMID 26438152, 2015).
lymphoma (1 paper, 2022). A malignant (clonal) proliferation of B- lymphocytes or T- lymphocytes which involves the lymph nodes, bone marrow and/or extranodal sites. "This experiment, originally performed before our RNA Seq and proteomic analysis of reimplanted Eμ-Myc lymphomas was completed, revealed lower levels of Claspin mRNA and protein expression in primary RelA T505A Eμ-Myc lymphomas, while ATR, CHK1, ATRIP, RAD17 and TOPBP1 were unaffected." (PMID 36240065, 2022).
cancer (10 papers, 2015 to 2025). A tumor composed of atypical neoplastic, often pleomorphic cells that invade other tissues. "Despite this, it was surprising that higher expression of several genes from clusters 1 and 2 (e.g., PRPF19 and ATRIP) were strongly associated with better overall survival in some cancer groups." (PMID 34853396, 2021). "The genes associated with cancer Hallmarks were GNAI2, RHOA, MAPKAPK3, HYAL1, and CISH, while the most connected were RHOA, MST1R, and ATRIP." (PMID 40028213, 2025). "We have demonstrated in our recent study that APE1 associates with ATR, ATRIP, and RPA to trigger the ATR-Chk1 DDR pathway activation in nuclear extract isolated from human cancer cells." (PMID 39112456, 2024). "The results confirmed the strong anti-cancer activity of cyclin-dependent kinase 12 and 13 (CDK12/13) inhibitors and the synergistic effect of THZ531 and pathway inhibitors (EGFR, RPTOR, ATRIP) regulated by cancer-related genes on the activity of HGSOC organoids." (PMID 38989138, 2024). "To further determine whether there existed difference of the activation of DNA damage checkpoint responses between radioresistant cancer cells and parental cells, we examined the expression levels of activating phosphorylated Chk1, Chk2, cdc25C, and ATRIP by western blotting after IR treatment." (PMID 29567990, 2018). "To validate the RNA-seq analysis, we selected seven representative genes on the basis of their relevance for HGSOC (PAX8, EGFR) and other cancers (GATA6, RBM47, KHDRBS3), or for their involvement in the DDR pathway (ATRIP, POLH)." (PMID 37202753, 2023). "Combined treatment with THZ531 and inhibitors of pathways regulated by these cancer relevant genes (EGFR, RPTOR, ATRIP) exerted synergic effects on HGSOC PDO viability." (PMID 37202753, 2023). "Carcinomas with homozygous deletions in either MRE11A, RAD50, ATRIP or PALB2, 4 genes that are essential for mammalian cell viability, are present in the publically available TCGA database." (PMID 26438152, 2015). "In addition, the cancer genome atlas (TCGA) database was interrogated for alterations in: 1) ATM, MRE11A, RAD50 and NBN; 2) ATR, ATRIP and TOPBP1; and 3) 15 FA genes." (PMID 26438152, 2015). "As ATRIP is not routinely included in standard hereditary cancer genetic testing panels, families like the one presented here may remain genetically unexplained despite exhaustive multigene panel testing." (PMID 41440239, 2025).
tumor (5 papers, 2017 to 2025). "Moreover, LOH analysis on the tumor DNA of ten available formalin-fixed paraffin-embedded (FFPE) samples of the ATRIP c.1152_1155del mutation carriers from Poland confirmed loss of the wild-type allele in four of ten tumor samples with the germline ATRIP c.1152_1155del variant." (PMID 41440239, 2025). "Furthermore, improved understanding of ATRIP-mutated tumor biology may ultimately help inform therapeutic decision-making." (PMID 41440239, 2025). "Although we previously showed that most ATRIP-mutated tumors have HRD, the direct association between loss of ATRIP function and resultant HRD in ATRIP-mutated tumor cells is indeed an area warranting further investigation." (PMID 41440239, 2025). "Overall, although direct evidence may still be lacking, the existing literature suggests that there could be a connection between loss of ATRIP function and compromised HRR in ATRIP-mutated tumor cells." (PMID 41440239, 2025). "As a tumor suppressor, SIRT2 maintains genome stability and prevents oncogenic transformations by regulating the DNA damage response through deacetylating key components like ATRIP (ATR-interacting protein) and CDK9 (Cyclin-dependent kinase 9)." (PMID 40710366, 2025). "Among these, the natural compound Shikonin specifically induces proteasome‐dependent degradation of ATM‐ATR Interacting Protein (ATRIP), inhibiting the activation of upstream regulatory factors in the DDR signaling pathway, thereby enhancing the sensitivity of tumor cells to chemotherapeutic agents." (PMID 41473689, 2025).
infection (4 papers, 2011 to 2025). The state of being infected such as from the introduction of a foreign agent such as serum, vaccine, antigenic substance or organism. "Moreover, infection with these virus serotypes also seemed to lead to relocalization of ATR-interacting protein (ATRIP) to viral replication centers and colocalization with RPA." (PMID 28791251, 2017). "Following infection, key components of the DDR, like ATM, RPA, ATRIP, 53BP1, γ-H2AX are recruited into viral replication centers, with PML NBs juxtaposed to these." (PMID 21998700, 2011). "An increase in the nuclear abundance of RPA complex components coincided with assembly of this complex in response to infection, consistent with previous findings that HSV-1 preferentially recruits Ataxia telangiectasia and Rad3-related-interacting protein (ATRIP)-RPA to support replication." (PMID 40577456, 2025).
ATRIP also shares sentences with these, for which no sentence is quoted: anemia (1 paper); breast tumors (1); genetic disorder (1); NBS-like disorder (1); Retinal dysplasia (1); Telangiectasia (1).